BRCA1 (BRCA1 DNA repair associated)
Diseases named in the same sentence as BRCA1 in open-access papers (continued):
Sharing a sentence is not in itself a finding about the gene and the disease.
breast cancer (continued). "BRCA1/2 are currently proven to be closely related to hereditary breast cancer and some sporadic breast cancer." (PMID 31998560, 2020). "We also explored the impact of HERV expression in its neighboring breast cancer development genes (BRCA1, CCND1, NBS1/NBN, RAD50, KRAS, PI3K/PIK3CA) and in long non-coding RNA expression (AC060780.1, also known as RP11-242D8.1)." (PMID 33194615, 2020). "Due to the genomic close proximity of the BRCA1 (breast cancer 1, early‐onset gene) and the BECN1 gene at the 17q21 chromosome, it was assumed that BECN1 deletions are rather a passenger event." (PMID 32935427, 2020). "Therefore, variants of genes other than BRCA1/2 may increase the breast cancer risk." (PMID 32013256, 2020). "In breast cancer, an onset about 20 years earlier (44 years in BRCA1 vs 64 years for sporadic BC) and a higher number of hormone receptor negative cancers are the main differences." (PMID 32719921, 2020). "For BRCA1/2-mutant breast cancer, wild-type breast cancer and corresponding normal tissues, three independent differentially expressed genes (DEGs) analysis were performed to validate potential hub genes with each other." (PMID 31998560, 2020). "The HRs for the breast cancer association decreased with age (PRS-by-age interaction HRs: BRCA1 HR = 0.996, P = 0.003; BRCA2 HR = 0.994, P = 9.40×10−5)." (PMID 32665703, 2020). "To date, BRCA1, BRCA2, PTEN, ATM, and CHEK2 have been sequentially reported as medium-to-high penetrant genes associated with breast cancer risk." (PMID 32879886, 2020). "The major cause is estimated to be the penetrance of the BRCA1 and BRCA2 founder mutation having increased over the last century, as observed by the Collaborative Group on Hormonal Factors in Breast Cancer." (PMID 33180852, 2020). "The goal of the current study was to estimate the prevalence of twenty alleles in six genes, BRCA1/2, CHEK2, PALB2, NBN, and RECQL, in Polish early-onset breast cancer patients." (PMID 32824581, 2020). "In 2005, two seminal papers were published demonstrating that breast cancer cells with siRNA depletion of BRCA1 or BRCA2 were exquisitely sensitive to the PARP inhibitor NU1025." (PMID 32183301, 2020). "The gene contributing most to the inherited breast cancer risk was BRCA2 (P = 3 × 10−10), accounting for 3.7% of the patients, followed by the gene BRCA1 that accounted for an additional 1.6% of the patients (P = 0.01)." (PMID 32318955, 2020). "Altogether, these results indicated that PRMT1 is an important component of the epigenetic defense of breast cancer cells against IR and that cytosolic BRCA1 is required for IR-induced apoptosis in breast cancer cells." (PMID 32764667, 2020). "To capture a high-risk population, such as women with germline BRCA1 and BRCA2 mutations, family breast cancer history, hormone therapy and smoking history, we assume an increase of breast cancer incidence by a factor of 5 over the baseline case." (PMID 32628726, 2020). "While PIK3CA alterations occur in 36% or more of breast cancer patients there are other relevant biomarkers to consider in these patients, including ERBB2, BRCA1, BRCA2, NTRK, and MSI (or mismatch repair deficiency)." (PMID 32976510, 2020). "There is clearly a very high rate of contralateral breast cancer approaching 4%–7% annually and significantly higher than BRCA1 or BRCA2 in those diagnosed aged <35." (PMID 33327514, 2020). "BRCA1, the breast cancer sensitivity gene, is involved in DNA damage repair and cell cycle progression." (PMID 33273900, 2020). "Targeted BRCA1/2 sequencing and whole exome sequencing were performed on 9 and 8 breast cancer patients respectively." (PMID 33240314, 2020).
breast cancer (continued). "BRCA1 mutation carriers develop breast and ovarian cancer at a younger age than BRCA2 mutation carriers, and BRCA2 is associated with fewer cases of breast cancer than BRCA1." (PMID 32455662, 2020). "In our previous study, twenty recurrent mutations were found in six breast-cancer-predisposing genes (BRCA1, BRCA2, CHEK2, PALB2, NBN, and RECQL) in Polish breast cancer patients." (PMID 32824581, 2020). "Detection of BRCA1 has great significance for the genetic analysis, early diagnosis and clinical treatment of breast cancer." (PMID 32698331, 2020). "Other mutations reported at lower prevalence (≤1.0%) in the 1108 familial breast cancer cases included BRCA1:c.3700_3704del (1.0% 10/1018), BRCA1:c.68_69del (0.9%, 9/1018), BRCA1:c.5251C>T (0.6%, 6/1018) and BRCA1:c.5346G>A (0.5%, 5/1108)." (PMID 32772980, 2020). "A recent meta-analysis explored the impact of BRCA1 and BRCA2 mutations on survival of ovarian and breast cancer, and claimed that these mutations should be considered when designing appropriate treatment strategies." (PMID 32096544, 2020). "BRCA1 mutations were more common (12.2% among breast cancer cases diagnosed at age 40 or below), while mutations in the BRCA2 gene were rare (0.08% in breast cancer patients diagnosed at age 40 or below)." (PMID 32824581, 2020). "In total, the panel covered about 80% of all BRCA1/2, CHEK2, PALB2, NBN, and RECQL mutation detection in Polish high-risk families with breast cancer." (PMID 32824581, 2020). "The breast cancer associated proteins BRCA1/2 function in the repair of DNA via homologous recombination; therefore, PARP inhibitors are approved for treatment of BRCA1/2 mutated breast, ovarian, and pancreas cancer." (PMID 32850380, 2020). "Summary statistics of a genome-wide association studies (GWAS) conducted using the Biobank Japan (BBJ), Breast Cancer Association Consortium (BCAC), and Consortium of Investigators of Modifiers of BRCA1/2 (CIMBA) are available to the public." (PMID 33167385, 2020). "Here we saw this behavior in the case of tissue HA levels but also in the case of some of colorectal and breast cancer patients for the expression of BRCA1 and BRCA2." (PMID 32610620, 2020). "Studies on breast cancer have shown that epigenetic silencing of RAD51C and BRCA1 by promoter methylation is strongly associated with signature 3 and is highly enriched in basal-like breast cancers." (PMID 33324554, 2020). "Patients with germline BRCA1 and BRCA2 mutations have annual risk of 2–6% for developing contralateral breast cancer." (PMID 33204419, 2020). "We found that many of these hub proteins have central roles in disease, such as insulin for both A1C measurement and Type 2 Diabetes, BRCA1 in Breast cancer, and Amyloid Precursor Protein in Alzheimer’s Disease." (PMID 32678846, 2020). "The present study aims to elucidate the underlying mechanism how PFKP is regulated by BRCA1 and the clinical significance of PFKP in breast cancer." (PMID 32470015, 2020). "BRCA1 and BRCA2 mutations are the most prevalent genetic drivers for hereditary breast cancer in humans." (PMID 32850393, 2020). "The BARD1 protein structure is like that of the BRCA1, however it is different from that of the BRCA2 (BReast CAncer type 2), the second gene associated with breast cancer." (PMID 33114377, 2020). "Four of the five previous reviews included women with BRCA1 and BRCA2 pathogenic germline gene variants, but only in the context of breast cancer risk." (PMID 32165993, 2020). "While the role of oestrogen with in growth of sporadic breast cancer has indeed been extensively studied, thepossible interaction among BRCA1 and hormone synthesis and actions in the field of BRCA1 has been strangely under-appreciated and under-investigated." (PMID 34803264, 2020). "In our cohort, 3% of primary breast cancer samples are BRCA1 methylated, which is in agreement with a recent study using data from The Cancer Genome Atlas." (PMID 32175521, 2020).
breast cancer (continued). "Nevertheless, Caucasian women, specifically Ashkenazi Jews who are carriers of BRCA1 and BRCA2 mutations, still have higher risk of developing breast cancer." (PMID 32183060, 2020). "Previous studies on BRCA1 have focused on its regulatory function in epithelial cells and tumors arising from these cells, the best-known being breast cancer." (PMID 32842712, 2020). "Currently, BRCA1/2-mutant mammary tumors are being treated with anti-PARP targeted therapies, including approximately 19.5% of TNBC." (PMID 32846967, 2020). "Our previous study found that the BRCA1 expression was decreased in breast cancer tissues, and its subcellular localization changed from the nucleus to cytoplasm." (PMID 33817238, 2020). "The breast cancer 1 and 2 (BRCA1/2) genes are tumor suppressor genes responsible for the synthesis of proteins involved in damaged DNA repair." (PMID 33194751, 2020). "While rare coding mutations in susceptibility genes such as BRCA1, BRCA2, and PALB2 confer a high risk of breast cancer, these account for less than one quarter of the familial risk." (PMID 31910858, 2020). "The results showed that BRCA1 insufficient breast cancer cells were more vulnerable to glucose deprivation, and consumed more glucose than their control group." (PMID 32470015, 2020). "To validate the SL phenotype in different genetic backgrounds, we performed survival experiments in two breast cancer models knockout (KO) for BRCA1." (PMID 33424604, 2020). "It has been demonstrated that 53BP1 expression in breast cancer is associated with poor prognosis, particularly in TNBC frequently showing BRCA1 dysfunction." (PMID 32283863, 2020). "Since the discovery of BRCA1 and BRCA2 genes 25 years ago, several other breast cancer susceptibility genes have been identified." (PMID 32481735, 2020). "In this context, we have recently provided evidence that the capacity of a specific IGF1R antibody to block IGF1-mediated IGF1R activation was impaired in mutant BRCA1-expressing breast cancer cells." (PMID 32391121, 2020). "BRAF, NRAS, and KIT are three well-known genes associated with melanoma, and BRCA1 and BRCA2 are two representative genes associated with breast cancer." (PMID 33121438, 2020). "Later, other studies have reported the same decreased activity of the NHEJ pathway in BRCA1-deficient HCC1937, and lymphoblastoid cell lines derived from breast cancer patients." (PMID 33013205, 2020). "Knowledge of BRCA1 and BRCA2 mutations has a significant clinical impact on the management and prevention of breast cancer." (PMID 32733560, 2020). "If TIAL1 has the same effect on BRCA1 protein expression in breast cancer, it is plausible that SNPs that increase TIAL1 expression also increase breast cancer risk, as is the case with rs3009879." (PMID 32714364, 2020). "Here, we show for the first time that stathmin protein expression by IHC is strongly related to BRCA1 positive breast cancers." (PMID 32076022, 2020). "We went on to test if the positive correlation between BRCA1 and 53BP1 expression levels in breast cancer samples are influenced by prognostic molecular profiling factors." (PMID 32139898, 2020). "A multi-centre prospective cohort of 2272 BRCA1 and 1605 BRCA2 mutation carriers was followed for a mean of 5.4 and 4.9 years, respectively; 426 women developed incident breast cancer." (PMID 31948486, 2020). "The prevalence of small, deleterious mutations in BRCA1 and BRCA2 genes in men with breast cancer is well established." (PMID 32952827, 2020). "Like BRCA1 and BRCA2 gene mutations, PALB2 mutations are also associated with high risk of breast cancer." (PMID 32824813, 2020). "BRCA1 and BRCA2 are the most studied breast cancer susceptibility genes that explain a significant proportion of hereditary breast and ovarian cancers." (PMID 33240314, 2020).
breast cancer (continued). "Results of our preclinical study on synergism between KLF4 and PARP1 have shed light on a novel therapeutic strategy for the BRCA1‐proficient population of TNBC breast cancer patients." (PMID 33231937, 2020). "In one study, differentially expressed genes were identified by comparing control MCF7 breast cancer cells with MCF7 cells ectopically expressing BRCA1." (PMID 32668577, 2020). "Combinatorial strategies involving PARP inhibitors with chemotherapy or immunotherapy are also being under investigation and hold promise for the future management of BRCA1/2 related breast cancer." (PMID 33194613, 2020). "HMMR forms a complex with BRCA1 and BRCA2, thus it has been identified as a high-risk factor in multiple cancer types such as breast cancer and fibrosarcoma." (PMID 32241274, 2020). "CST cells are about 10-fold resistant to paclitaxel compared to most BRCA1-proficient breast cancer cell lines." (PMID 32053991, 2020). "PARPi treatment also reduces the transcription of DDX21, which leads to the inhibition of rDNA transcription and ribosome biogenesis in BRCA1/2 proficient breast cancers leading to reduced cancer growth." (PMID 33015058, 2020). "In comparison with BRCA1-mutated cancer, BRCA2-mutated breast carcinomas frequently express ER and PGR; additionally, HER2 is expressed at the same frequency." (PMID 32269964, 2020). "Current U.S. guidelines limit BRCA1/2 genetic testing to individuals with a personal or family history of a relevant cancer, including early-onset breast cancer, multiple primary breast cancers, ovarian cancer, and certain other cancers." (PMID 32376921, 2020). "Pathogenic variants in the BRCA1 and BRCA2 genes are linked to an increased risk for female breast and ovarian cancer (including early-onset breast cancer), male breast cancer, prostate cancer, pancreatic cancer, and certain other cancers." (PMID 32376921, 2020). "Deleterious germline PV carriers in BRCA1 or BRCA2 have an elevated lifetime risk of developing breast and/or ovarian cancer, particularly 60–80% for breast cancer (BC) and 26–54% for BRCA1 and 10–23% for BRCA2 for ovarian cancer (OC)." (PMID 32438681, 2020). "Several FA genes, such as BRCA1/FANCS, BRCA2/FANCD1, PALB2/FANCN, and RAD51C/FANCO have been confirmed to be breast carcinoma susceptibility genes at present." (PMID 32300589, 2020). "There were 49 DCIS in 325 breast cancers, and nine cases out of sixty‐two BRCA mutation were DCIS, 2% (n = 1) carried a BRCA1 mutation, and 16.4% (n = 8) carried a BRCA2 mutation." (PMID 30652428, 2019). "The Hereditary Breast and Ovarian Cancer (HBOC) syndrome is caused by loss-of-function mutations in the BRCA1 and BRCA2 genes and explains approximately 16% of inherited breast cancers." (PMID 30781715, 2019). "BRCA1 and BRCA2 are tumor suppressor genes typically mutated in breast cancer and highly connected with cancer aggressiveness and survival." (PMID 32010625, 2019). "The disproportionately high rate of mortality compared with hormone receptor positive breast cancer or HER2 positive breast cancer is largely due to the lack of effective targeted therapies, with the exception of tumors with germline BRCA1/2 mutation." (PMID 31101835, 2019). "We also found that reconstitution of BRCA1 resulted in significant increase of the breast cancer cell population expressing high levels of the differentiation-associated CD24 cell surface protein without significantly affect CD24 mRNA levels." (PMID 31273285, 2019). "The authors concluded that the BRCA1/NEAT1/miR‐129‐5p signaling axis contributes to breast cancer tumorigenesis." (PMID 30430751, 2019). "It has been reported that frequency of LGRs ranges from approximately 6–27% of all detected BRCA1 pathogenic variants, and BRCA2 LGRs play a less role in hereditary breast cancer patients." (PMID 31174498, 2019).
breast cancer (continued). "MCF-7 breast cancer cells with BRCA1 knockdown were more sensitive to pan-mTOR inhibitor PP242 and pan-PI3K/pan-mTOR inhibitor PKI-179 than cells with the non-targeting scrambled control." (PMID 31771139, 2019). "miR-218 targeted BRCA1 to sensitize breast cancer cells against cisplatin and miR-542-3p silencing restored trastuzumab resistance via PI3K-AKT pathway regulation in breast cancer cells." (PMID 31009516, 2019). "Inhibition of BRCA1 and BRCA2 expression by FR suggested a synergistic cytotoxic effect with olaparib based on the fact that this PARP1 inhibitor is effective in breast cancer with genetic deficiencies in BRCA1 or BRCA2." (PMID 30719229, 2019). "The breast cancer 1 (BRCA1) and breast cancer 2 (BRCA2) genes normally behave as tumor suppressor genes and can maintain cell proliferation and differentiation." (PMID 31182966, 2019). "BRCA1 promoter methylation in blood has previously been reported to be higher in breast cancer patients compared with controls by some studies, but not others." (PMID 31101124, 2019). "Since the identification of breast cancer genes BRCA1/2 in 1994 and 1995, respectively, a large amount of data on the risks conferred by these genes for breast and other cancers has been generated." (PMID 31658756, 2019). "Spontaneously uced rat mammary tumors and human breast cancer tissues with high levels of CTSS expression showed low BRCA1 expression." (PMID 30006610, 2019). "In this study, we examined the role of the tumor suppressor BRCA1 and hypoxia in the regulation of cancer cell stemness using genetically matched breast cancer cell lines." (PMID 31273285, 2019). "In the present study, the recurrent 5382inC BRCA1 germline mutation was identified in two postmenopausal women with TNBC diagnosed at the age of 50 and 57 and presenting a family history of breast cancer." (PMID 30975216, 2019). "One possible mechanism of carcinogenic action of BLV and its close relative HTLV (human T-cell leukemia virus) is inhibition of cellular DNA repair, consistent with how certain mutated genes (BRCA1 and BRCA2) contribute to the development of breast cancer." (PMID 31892207, 2019). "Here, we report that BRCA1 and BRCA2-deficient breast cancers were associated with features of genomic instability including increased mutation burden." (PMID 31022191, 2019). "Rare non-protein-truncating variants were detected with the same frequency (0.6%) in 3548 non-BRCA1/2 familial breast cancer cases and 1,435 controls from the Netherlands." (PMID 31463769, 2019). "Taken together, BRCA1- and BRCA2-deficient breast cancers demonstrated higher degree of genomic instability compared to BRCA-proficient breast cancers." (PMID 31022191, 2019). "There are also descriptions of LGRs in BRCA1/2 in breast cancer patients from Peru, Puerto Rico, and Uruguay." (PMID 31658756, 2019). "The interplay between mTORC1/2 signaling on the DDR and the sensitivity of breast cancer cell lines with impaired BRCA1 status to mTORC1/2 inhibition also suggests the potential for tailored treatment based on the patient’s underlying genetics." (PMID 31771139, 2019). "Some such changes have already shown clinical relevance, such as BRCA1 in breast cancer, MGMT in glioblastoma multiform, and SEPT9, which has been approved by the Food and Drug Administration (FDA) for the diagnosis of colon cancer." (PMID 31452839, 2019). "We also observed that the odds of being an ER + PR+ breast cancer case was enhanced among women with late age at first birth (> 27 years) in the presence of unmethylated BRCA1 promoter." (PMID 31533668, 2019). "In breast cancer models, ERβ impairment of DNA damage response involves BRCA1 downregulation and caspase-2 activation which results in mitotic catastrophe and decreased cancer cell survival." (PMID 30992459, 2019). "Pathogenic BRCA1 and BRCA2 variants were identified in 7% of the investigated patients with breast cancer." (PMID 31263571, 2019).